PPP1R18 (protein phosphatase 1 regulatory subunit 18)
Description:
[Isoform 1]: May target protein phosphatase 1 to F-actin cytoskeleton. [Isoform 4]: May target protein phosphatase 1 to F-actin cytoskeleton.
Synonyms: HKMT1098; KIAA1949; phostensin
Tractability: Antibody: the Human Protein Atlas places it where antibodies can reach. PROTAC: ubiquitination databases record sites on it; its protein half-life has been measured.
Safety:
Unwanted effects reported when the protein is acted on. In parentheses: how it was acted on, where the effect was seen, and who reports it.
thrombocytopenia (source: ClinPGx)
Gene: Protein-coding gene on chromosome 6 (30,676,389 to 30,687,895, reverse strand). Ensembl gene ENSG00000146112.
Subcellular location: Cytoplasm, cytoskeleton (Isoform 1); Cytoplasm, cytoskeleton (Isoform 4)
Subcellular location (Human Protein Atlas): Plasma membrane; Nucleoplasm
Gene Ontology:
Molecular function: protein binding; phosphatase binding
Cellular component: cytoskeleton
Genetic constraint (gnomAD): Loss-of-function variants: 31 observed, 54.78 expected, observed/expected ratio (o/e) 0.57, 90% interval 0.42 to 0.76. The upper end of that interval is the gene's LOEUF score, 0.76, which puts it in group 3 of 6, group 1 being the genes least tolerant of losing a copy. Missense variants: 658 observed, 752.79 expected, observed/expected ratio (o/e) 0.87, 90% interval 0.82 to 0.93. Synonymous variants: 304 observed, 309.75 expected, observed/expected ratio (o/e) 0.98, 90% interval 0.89 to 1.08.
Homologues: Orthologues: chimpanzee PPP1R18 (99% identical), macaque PPP1R18 (97% identical), pig PPP1R18 (85% identical), dog PPP1R18 (82% identical), rat Ppp1r18 (76% identical), mouse Ppp1r18 (74% identical), guinea pig PPP1R18 (61% identical), zebrafish ppp1r18 (22% identical), tropical clawed frog ppp1r18 (22% identical). Paralogues in human: TPRN (22% identical).
Diseases named in the same sentence as PPP1R18 in open-access papers:
PPP1R18 is named in the same sentence as 18 diseases in open-access papers, as found by Europe PMC text mining. Sharing a sentence is not in itself a finding about the gene and the disease. The quoted sentences say what the papers report.
esophageal cancer (2 papers, 2017 to 2023). A primary or metastatic malignant neoplasm involving the esophagus. "Five nucleoproteins MISP, KLF10, KLF15, PPP1R18, and RXRβ were identified by oligonucleotide trapping, as the binding factors on the TRE under TPA stimulation, and were expressed at varying expression levels in esophageal cancer." (PMID 29098164, 2017). "Several nucleoproteins (MISP, KLF10, KLF15, PPP1R18, and RXRβ) have been identified by affinity chromatography and mass spectrometry and could respond to TPA stimulation and regulate LCN2 expression in esophageal cancer cells." (PMID 29098164, 2017).
myopia (2 papers, 2023 to 2024). "The results revealed that NR1D1, PPP1R18, PGBD2, and PPP1R3D genes were associated with myopia, and these genes were potential biomarkers for myopia." (PMID 39597899, 2024). "The biomarkers selected by both algorithms were plotted in a Venn diagram, and a total of 4 genes (NR1D1, PPP1R18, PGBD2, PPP1R3D) were identified as biomarkers of myopia in the overlapping part." (PMID 37740201, 2023). "Our study shows that NR1D1, PPP1R18, PGBD2, and PPP1R3D are effective as biomarkers in the diagnosis of myopia and that NR1D1, PPP1R18, PGBD2, and PPP1R3D may be potential therapeutic targets." (PMID 37740201, 2023).
ankylosing spondylitis (1 paper, 2023). An autoimmune chronic inflammatory disorder characterized by inflammation in the vertebral joints of the spine and sacroiliac joints. "CYP21A2, as well as MSH5, PPP1R18, and NEU1 have been demonstrated by previous GWASs associated with other autoimmune disorders such as RA, ankylosing spondylitis (AS), T1DM, and SLE." (PMID 37197658, 2023).
gastric cancer (1 paper, 2015). A primary or metastatic malignant neoplasm involving the stomach. "Aberrant methylation at the genes B3GATL4 (6p21.3), TNXB (6p21.3), TRIM31 (6p21.3), LY6G5C (6p21.33), KIAA1949/PPP1R18 (6p21.3), and GNL1 (6p21.3) identified in NPC was also hypermethylated in EBV-positive gastric cancers compared to EBV-negative gastric cancers (FDR < 1.6 × 10−90)." (PMID 25924914, 2015).
liver fibrosis (1 paper, 2021). "Significant reductions in PPP1R18 methylation have been recorded in patients with severe liver fibrosis, suggesting that epigenetic disorders are involved in the progression of the disease." (PMID 34796198, 2021).
osteosarcoma (1 paper, 2023). A usually aggressive malignant bone-forming mesenchymal neoplasm, predominantly affecting adolescents and young adults. "However, recurrent gene fusions in pediatric cancers rarely involve these regions, with only two cases validated in 48 tumors from the MOSCATO-01 cohort (two translocations t and generating GPANK1::ABHD16A and PPP1R18::FXR2 gene fusions in eRMS and osteosarcoma cases, respectively)." (PMID 38318504, 2023).
type 2 diabetes (1 paper, 2022). "For example, cg11554650 (PPP1R18) colocalized with type 2 diabetes, and was driven by a single nucleotide polymorphism (rs2516396)." (PMID 36380121, 2022).
tumor (3 papers, 2023 to 2026). "Knockdown of PPP1R18 substantially impaired ccRCC cell proliferation, migration, and invasion in vitro and suppressed tumor growth in vivo." (PMID 42108458, 2026). "What’s more, literature reports that PPP1r18 can promote ESCC tumor progression via activating calcineurin-mediated ERK pathway." (PMID 39473097, 2025). "In the ICGC dataset, CFB and PPP1R18 were significantly upregulated in tumor samples, whereas TOM1L1 was significantly downregulated in tumor samples." (PMID 36611973, 2023). "In the three GEO datasets, the expression of CFB and PPP1R18 was significantly higher in tumor samples, whereas that of TOM1L1 was significantly lower." (PMID 36611973, 2023). "Compared to nondistant metastatic ccRCC tissues and normal tissues, the expression patterns of CFB and PPP1R18 were significantly higher in distant metastatic ccRCC samples and tumor samples, whereas the expression of TOM1L1 was significantly lower." (PMID 36611973, 2023).
cancer (2 papers, 2023). A tumor composed of atypical neoplastic, often pleomorphic cells that invade other tissues. "Among the 19 cancer types, PPP1R18/KIAA1949 (p = 2.98 × 10−32) and TOM1L1 (p = 3.87 × 10−30) exhibited the highest specificity for KIRC/ccRCC, and CFB also presented excellent specificity for KIRC/ccRCC (p = 3.76 × 10−13)." (PMID 36611973, 2023).
PPP1R18 also shares sentences with these, for which no sentence is quoted: autoimmune disease (1 paper); autoimmune disorders (1); clear cell renal cell carcinoma (1); coronary artery disease (1); esophageal squamous cell carcinoma (1); hypertriglyceridemia (1); non-melanoma skin carcinoma (1); schizophrenia (1); viral infections (1).